AGT (angiotensinogen)
Diseases named in the same sentence as AGT in open-access papers (continued):
Sharing a sentence is not in itself a finding about the gene and the disease.
glomerulonephritis (13 papers, 2009 to 2024). A renal disorder characterized by damage in the glomeruli. "By evaluating the expression level of angiotensinogen (AGT) in glomerulonephritis and urinary AGT (uAGT), it becomes feasible to evaluate the extent of RAS activation within the renal region and determine the pathological state of chronic glomerulonephritis." (PMID 38239353, 2023). "In our previous study including biopsy-proven glomerulonephritis patients, patients with high urinary AGT and renin showed significantly decreased proteinuria and increased eGFR during RAS-inhibitor treatment." (PMID 32410703, 2020).
Hyperkalemia (13 papers, 2012 to 2025). An abnormally increased potassium concentration in the blood. "Plasma renin, angiotensinogen, angiotensin-I, angiotensin-II, and aldosterone were measured to assess the role of the RAAS axis in volume-related lower blood pressure and hyperkalemia." (PMID 36803854, 2023). "No acute kidney injury or hyperkalemia was observed in animal studies following AGT silencing." (PMID 39852196, 2024).
colitis (12 papers, 2016 to 2025). Inflammation of the colon. "An increase in angiotensinogen (Agt) expression during colitis could therefore occur through increased sympathetic signaling, inflammatory cytokines, increased renin secretion through reduced SCFAs, and enhanced ACE and AngII receptor type 1 (AT1R) signaling through LPS." (PMID 40723857, 2025).
Glucose intolerance (12 papers, 2012 to 2025). Glucose intolerance (GI) can be defined as dysglycemia that comprises both prediabetes and diabetes. "Along the same lines, mice overexpressing AGT in adipose tissue also develop glucose intolerance on a low-fat diet, which is not further exacerbated by high-fat feeding." (PMID 23308073, 2012).
IgA nephropathy (12 papers, 2009 to 2024). "IgA nephropathy increased AGT and Ang II immunoreactivity along the tubule, and AGT was present in glomeruli." (PMID 35710133, 2022). "In a study by Nishiyama and colleagues, urinary AGT (UAGT) levels were raised in patients with IgA nephropathy, and this was shown to correlate with renal tissue gene expression of AGT and angiotensin II immunoreactivity." (PMID 35626799, 2022). "Greater AGT and Ang II immunoreactivity was also observed in glomeruli from pediatric patients with IgA nephropathy." (PMID 35710133, 2022). "Several clinical studies have shown that urinary angiotensinogen is significantly increased in patients with CKD including IgA nephropathy, diabetic nephropathy, polycystic kidneys, focal segmental glomerulosclerosis." (PMID 29600408, 2018). "In patients with minor glomerular abnormality and IgA nephropathy, urinary angiotensinogen/creatinine ratio is highly correlated with gene expression of angiotensinogen in renal biopsy tissues." (PMID 29600408, 2018). "It was reported that UAGTCR was correlated with mRNA and protein levels of AGT in renal tissues with IgA nephropathy." (PMID 27801805, 2016).
gastric cancer (11 papers, 2010 to 2025). A primary or metastatic malignant neoplasm involving the stomach. "This study found that AGT is highly expressed in gastric cancer and up-regulated with the increase of the stage." (PMID 35600357, 2022). "The results show that, compared with normal tissues, the expression of AGT and NrCAM in gastric cancer was significantly up-regulated while the expression of the other eight genes was down-regulated in gastric cancer." (PMID 35600357, 2022). "The results based on sample sequencing also show that the expression of AGT was up-regulated in gastric cancer as compared with the standard group." (PMID 35600357, 2022). "In conclusion, the expression of AGT is up-regulated in gastric cancer and the gastric cancer stages, and its continuous up-regulation is closely related to the poor prognosis of patients with gastric cancer." (PMID 35600357, 2022). "The upregulated expression and hypomethylation of AGT were found in gastric cancer, and there was a negative association between the prognosis of gastric cancer and AGT expression." (PMID 40836964, 2025). "After expression analysis and the observation of the expression in the stages of gastric cancer, we found that AGT and NrCAM were up-regulated in gastric cancer and that their appearance could increase with the increase of the stage." (PMID 35600357, 2022). "It is suggested that AGT may contribute to gastric cancer progression and could be used as a potential biomarker or therapeutic target in gastric cancer." (PMID 35600357, 2022). "AGT has prominent abnormal expression in gastric cancer and may promote gastric cancer progression." (PMID 35600357, 2022). "Therefore, we collected gastric cancer tissue samples for transcriptome analysis to further observe the expression of AGT and NRCAM in gastric cancer." (PMID 35600357, 2022). "The results revealed that exosomal AGT, SERPINH1 and MMP7 may serve as biomarkers for gastric cancer diagnosis and prognosis and involved in GC progression." (PMID 34215253, 2021).
glioblastoma (11 papers, 2004 to 2025). The most malignant astrocytic tumor (WHO grade IV). "In recurrent glioblastoma patients, a high RNA expression of the angiotensinogen gene (AGT) in tumor tissue has been found associated with nonresponse to bevacizumab combination therapy." (PMID 32133779, 2020). "Prospective clinical trials are needed to evaluate the efficacy of this combination regimen and to what extent AGT promoter methylation is associated with efficacy in recurrent glioblastoma patients." (PMID 32133779, 2020). "In summary, we found promoter methylation of the gene encoding angiotensinogen as being associated with response to bevacizumab combination therapy in recurrent glioblastoma patients." (PMID 32133779, 2020). "Furthermore, low expression of AGT has been associated with a favourable response to the anti-angiogenic treatment, bevacizumab, in glioblastoma patients at progression." (PMID 38607073, 2024). "In conclusion, we have successfully developed [99mTc]Tc-AGT-7, a theranostic compound inspired by the glioblastoma tumor-homing properties of [99mTc]Tc-TF, designed to combine both diagnostic and therapeutic functionalities." (PMID 40872566, 2025). "Angiotensinogen is known to be expressed within the brain and highly expressed in glioblastoma patient samples." (PMID 38607073, 2024). "The majority of genes (ATP6AP2, AGTR1, ACE, and AGT) were consistently expressed in glioblastoma cases, with the exception of AGTR2 and REN." (PMID 38607073, 2024). "The MGMT promoter has been an important target in both newly diagnosed glioblastoma and recurrent glioblastoma as the protein product, AGT, yields resistance to alkylating chemotherapy such as TMZ." (PMID 38928445, 2024). "An extensively studied epigenetic mechanism that regulates disease progression in glioblastoma is MGMT, which encodes the DNA repair protein O6-alkylguanine (O6-AG) DNA alkyl transferase (AGT)." (PMID 38928445, 2024). "Human glioblastoma cells express immunohistochemistry demonstrable renin and angiotensinogen mRNAs and proteins, as well as renin and angiotensin 1 or 2 receptors." (PMID 23594434, 2013). "Human glioblastoma and glioblastoma cells expressed renin, AGT, renin receptor, AT2 and/or AT1 mRNAs and proteins determined by RT–PCR and/or Western blotting, respectively." (PMID 14997208, 2004). "Furthermore, AGT-7 was specifically designed to selectively target glioblastoma while minimizing undesirable off-target localization, particularly in the myocardium, which is a known site of accumulation for [99mTc]Tc-TF." (PMID 40872566, 2025). "Throughout the 24-h study period, [99mTc]Tc-AGT-7 exhibited low uptake in all other evaluated organs, reinforcing its target specificity and capitalizing on its potential as a safe and effective theranostic tool for glioblastoma." (PMID 40872566, 2025). "Interestingly, AGT was higher in expression in both glioblastomas and low-grade gliomas, while REN expression was comparatively lower when compared to the majority of the other tumour types." (PMID 38607073, 2024). "One explanatory factor is that DNA demethylation of the CEBP region in the AGT promoter may occur from the time of glioblastoma diagnosis to the time of glioblastoma recurrence as a result of continues AGT gene activation." (PMID 32133779, 2020). "Therefore, in the present study, we report the expression and functions of renin, AGT and angiotensin peptides in human glioblastoma tumours and human glioblastoma cells in culture." (PMID 14997208, 2004). "Because AGT expression is epigenetically regulated, we aimed to investigate whether AGT promoter methylation in tumor tissue predicts response to bevacizumab combination therapy in patients with recurrent glioblastoma." (PMID 32133779, 2020). "Thus, human glioblastoma cells produce renin and AGT and secrete AGT." (PMID 14997208, 2004).
glioblastoma (continued). "Progression-free survival (PFS) and overall survival (OS) were compared across TCGA glioblastoma cases, stratified from high and low expression of ATP6AP2, AGTR1, AGTR2, ACE, AGT, and REN genes." (PMID 38607073, 2024). "In cases of glioblastoma within the TCGA, ATP6AP2, AGTR1, ACE, and AGT had consistent expressions across samples, while AGTR2 and REN were lowly expressed." (PMID 38607073, 2024). "Baseline expressions of RAS genes were relatively similar to the TCGA glioblastoma cohort, where REN and AGTR2 were very lowly expressed while ATP6AP2, AGTR1, ACE, and AGT were consistently expressed." (PMID 38607073, 2024). "Here, we investigated the gene expression of RAS components (ATP6AP2, AGTR1, AGTR2, ACE, AGT, and REN) in glioblastoma patient samples from The Cancer Genome Atlas (TCGA) and their association with survival outcomes and the expression of TME pathways." (PMID 38607073, 2024). "ATP6AP2, AGTR1, AGTR2, AGT, and ACE had low frequencies of CNAs (<1%) in glioblastomas; however, REN was altered in 6% of glioblastoma cases." (PMID 38607073, 2024). "We studied the expression of RAS-related genes (ATP6AP2, AGTR1, AGTR2, ACE, AGT, and REN) in The Cancer Genome Atlas (TCGA) glioblastoma cohort, their relationship to patient survival, and association with tumour microenvironment pathways." (PMID 38607073, 2024). "The baseline mRNA expression of RAS genes (ATP6AP2, AGTR1, AGTR2, AGT, ACE, and REN) were explored in 12 patient-derived glioblastoma cell lines." (PMID 38607073, 2024). "The combination of TMZ + RT resulted in a slight but significant increase in the expression of ATP6AP2, AGTR1, and ACE, while AGT and the lowly expressed AGTR2 and REN remained unchanged across all 12 glioblastoma cell lines." (PMID 38607073, 2024). "The expression of angiotensinogen, (pro)renin, ACE, and AT1 and AT2 receptors has been demonstrated in glioblastoma tumours and glioblastoma cells in culture, in which renin has a direct role in proliferation and/or survival." (PMID 16755291, 2006). "Renin and angiotensinogen (AGT) mRNAs and proteins were found by in situ hybridisation and immunohistochemistry in glioblastoma cells." (PMID 14997208, 2004). "Immunohistochemistry for AGT performed on normal tissue, and grade II and III astrocytoma and glioblastoma multiform (grade IV) suggested that the expression of this protein was inversely related to tumour grading (manuscript in preparation)." (PMID 14997208, 2004). "In the present study, we demonstrate that AGT, prorenin, ACE, AT1 and AT2 are synthesised and expressed in human glioblastoma and glioblastoma cells in culture, however at different levels of expression between the specimens." (PMID 14997208, 2004). "Conversely, AGT and REN had lower expressions in glioblastomas compared to low-grade gliomas." (PMID 38607073, 2024). "In this study of 77 recurrent glioblastoma patients, a low methylation of the CEBP binding region in the AGT promoter was found significantly associated with a lack of response to bevacizumab combination treatment." (PMID 32133779, 2020). "Our results suggest that the methylation status of the AGT promoter can be used to identify recurrent glioblastoma patients, with a specificity of 96%, who will not respond to bevacizumab combination therapy." (PMID 32133779, 2020). "Taken together, our findings suggest that low AGT promoter methylation in tumor tissue predicts nonresponse to bevacizumab combination treatment in patients with recurrent glioblastoma." (PMID 32133779, 2020). "The relatively low sensitivity of our predictive model suggests that AGT promoter methylation at the time of glioblastoma diagnosis is not the only factor influencing lack of response to bevacizumab combination treatment." (PMID 32133779, 2020). "Together, these results suggest that human glioblastoma cells have the potential to produce AGT, prorenin/renin and Ang I, but not to convert Ang I into Ang II." (PMID 14997208, 2004).
glioblastoma (continued). "Renin expression has been previously demonstrated by immunohistochemistry in human glioblastoma and AGT synthesis by Northern blotting in nontumoral (n=3) and tumoral (n=3) astrocytic cell lines." (PMID 14997208, 2004). "Accordingly, the aim of this study was to investigate whether lower AGT promoter methylation in tumor tissue is predictive for glioblastoma patients not responding to bevacizumab combination therapy." (PMID 32133779, 2020). "AGT mRNA and protein were expressed by nontumoral astrocytes and glioblastoma cells." (PMID 14997208, 2004). "We showed that AGT, TDP renin substrate and Ang peptides did not play any role in glioblastoma cell growth, apoptosis and/or DNA synthesis." (PMID 14997208, 2004). "Angiotensinogen, des(Ang I)AGT, tetradecapaptide renin substrate (AGT1–14), Ang I, Ang II or Ang III, added to glioblastoma cells in culture, did not modulate their proliferation, survival or death." (PMID 14997208, 2004). "The majority of glioblastoma cases expressed ATP6AP2, AGTR1, ACE, and AGT but not AGTR2 and REN." (PMID 38607073, 2024).
kidney inflammation (11 papers, 2010 to 2024). "Recent systematic review of urine biomarkers in children with IgAVN showed that the most promising urinary biomarkers in predicting nephritis were kidney injury molecule-1 (KIM-1), monocyte chemotactic protein-1 (MCP-1), N-acetyl-β-glucosaminidase (NAG), and angiotensinogen (AGT)." (PMID 35372148, 2022). "Urinary angiotensinogen was also significantly increased when comparing those with IgAV-N to those without (IgAVwoN), suggesting the RAAS system may be activated in IgAV regardless of nephritis." (PMID 37755547, 2023). "The most promising pre-clinical urinary biomarkers in predicting presence of nephritis were as follows: kidney injury molecule-1 (KIM-1) (AUC 0.93), monocyte chemotactic protein-1 (MCP-1) (AUC 0.83), N-acetyl-β-glucosaminidase (NAG) (0.76–0.96), and angiotensinogen (AGT) (AUC not available)." (PMID 33993342, 2021).
malignant hypertension (11 papers, 2010 to 2025). Severe hypertension that is characterized by rapid onset of extremely high blood pressure and hypertension-mediated organ damage. "Double transgenic rats (dTGR) harbouring human renin and human angiotensinogen genes develop malignant hypertension due to increased angiotensin II formation." (PMID 20721338, 2010). "Increases in urinary albumin and angiotensinogen were observed with malignant hypertension, although the latter did not reflect changes in angiotensinogen gene expression in the kidney cortex." (PMID 27935823, 2016).
glioma (10 papers, 2005 to 2025). A benign or malignant brain and spinal cord tumor that arises from glial cells (astrocytes, oligodendrocytes, ependymal cells). "The angiotensinogen rs5050 GC genotype is related to poor prognosis in patients with glioma; this germline genetic variant has been proposed as a biomarker." (PMID 39063232, 2024). "This reduced cardiac uptake, attributed to the lower lipophilicity of [99mTc]Tc-AGT-7, highlights its promise as a potential glioma-targeted theranostic agent." (PMID 40872566, 2025). "The reduced heart uptake of [99mTc]Tc-AGT-7 is especially desirable, as an excessive myocardial accumulation would impair its effectiveness and safety as a glioma theranostic agent." (PMID 40872566, 2025). "The low angiotensinogen promoter methylation observed in patients with recurrent gliomas is related to nonresponse to bevacizumab combination treatment with chemotherapy." (PMID 39063232, 2024).
pancreatic cancer (10 papers, 2010 to 2025). "GSEA also further confirmed the plausibility of the PPI results, e.g. ABL protein enrichment in the pancreatic adenocarcinoma pathway, pancreatic cancer, CPB1 enrichment in the metabolism of angiotensinogen to angiotensins, and peptide hormone metabolism." (PMID 36261459, 2022).
psoriasis (10 papers, 2011 to 2024). An autoimmune condition characterized by red, well-delineated plaques with silvery scales that are usually on the extensor surfaces and scalp. "Transcriptome analysis showed that SerpinA8 (AGT) is one of the differentially expressed genes in mild psoriasis." (PMID 39737188, 2024). "Polymorphisms in both ACE and other angiotensinogen genes have been associated with susceptibility to inflammatory diseases such as SLE and psoriasis with frequent tonsillitis." (PMID 23437094, 2013). "Researchers proposed that adipose tissue in psoriasis patients serves as a major source of angiotensinogen, which is subsequently converted to angiotensin II." (PMID 21479272, 2011). "AGT(SerpinA8) and SerpinB8 are susceptibility gene for psoriasis, but the specific mechanism has not been studied." (PMID 39737188, 2024).
cerebrovascular diseases (9 papers, 2012 to 2023). "(ii) Moreover, we identified that AGT M235T (p = 0.04) and AGT T174M (p = 0.04) polymorphisms were associated with high risk for this cerebrovascular disease in this group of patients." (PMID 38025202, 2023).
cognitive decline (9 papers, 2016 to 2026). "They found that the medication was protective against cognitive decline in AA carriers of AGT 6AG (rs5051), and in CC homozygotes of the AGT M235T (rs699) polymorphism, both associated with higher angiotensinogen levels." (PMID 34302265, 2021).
colorectal cancer (9 papers, 2017 to 2025). A primary or metastatic malignant neoplasm that affects the colon or rectum. "To date, the AGT gene has been confirmed to be closely related to the occurrence and development of various types of diseases, including cardiovascular disease and colorectal cancer." (PMID 36836041, 2023). "Studies have shown that AGT can also inhibit the invasion and migration of colorectal cancer." (PMID 35600357, 2022).
endometrial cancer (9 papers, 2021 to 2025). Primary or metastatic malignant neoplasm involving the endometrium (mucous membrane that lines the endometrial cavity). "Therefore, both high estrogen levels and obesity, which have the propensity to enhance AGT production, are substantial risk factors for endometrial cancer, thereby accelerating sickness." (PMID 37869088, 2023). "Specifically, they examined the prevalence of RAS-related single-nucleotide polymorphisms and showed that AGT levels were less prevalent in women with endometrial cancer than in controls, and AGT caused the removal of angiotensin I; both are anti-angiogenic factors." (PMID 35812749, 2022).
hyperuricemia (9 papers, 2014 to 2023). An abnormally high level of uric acid. "Hyperuricemia has been proven to upregulate the expression of angiotensinogen, angiotensin-converting enzyme, and angiotensin II receptors and increase angiotensin II levels." (PMID 34221283, 2021).